INS (insulin)
Diseases named in the same sentence as INS in open-access papers (continued):
Sharing a sentence is not in itself a finding about the gene and the disease.
Hyperinsulinemia (continued). "Thus, nutritionally driven hyperinsulinemia may disturb the normal balance of the insulin–GH–IGF-I axis by shifting the insulin : GH ratio towards insulin (and IGF-I) and away from GH." (PMID 36901984, 2023). "LGA infants may have increased intrauterine exposure to excess nutrients, especially glucose, which can lead to hyperinsulinemia, increased use of oxygen and glucose, and oxidative stress, resulting in increased lipolysis and reduced insulin sensitivity at birth." (PMID 37328759, 2023). "Furthermore, given that IDE is more insulin-selective than Aβ, brain hyperinsulinemia may impact the clearance of Aβ, favoring its cerebral accumulation and its consequent neuroaccumulation." (PMID 37372995, 2023). "In addition, overnutrition leads to weight gain and carbohydrate intolerance which lead to the development of IR/hyperinsulinemia, ketogenic diets reduce visceral obesity and increase insulin sensitivity, and the therapeutic carbohydrate-restricted diet can prevent or reverse IR." (PMID 37378117, 2023). "The most frequent genetic cause of hyperinsulinism and neonatal diabetes is pathogenic mutations in KCNJ11 and ABCC8; the subunits of the β-cell ATP-sensitive potassium channel, a crucial element of the glucose-stimulated insulin secretion pathway, are encoded by these genes." (PMID 38283146, 2023). "Indeed, recent studies have demonstrated that both the mechanical and metabolic components of the exercise pressor reflex are potentiated by insulin, suggesting that hyperinsulinemia may play a role in exaggerating the exercise pressor reflex in T2DM." (PMID 36703927, 2022). "Moreover, bearing in mind that insulin also stimulates growth and triggers many signaling cascades, hyperinsulinemia boosts the serine phosphorylation of IRS-1 (Ser375), MEK1/2, ERK1/2, S6K1, and PI3K p110a, decreases tyrosine phosphorylation IRS-1, and the p85 subunit of PI3K is not changed." (PMID 35454166, 2022). "It has been hypothesized that decreased hepatic conversion of cortisone into cortisol due to hyperinsulinemia-suppressed 11β-HSD1 activity in the liver represents a physiological mechanism to improve hepatic insulin sensitivity and to lower fasting plasma glucose levels." (PMID 35897752, 2022). "This last observation suggests a vicious circle during the early stages of hyperinsulinemia, whereby high insulin levels lead to a reduction in adiponectin levels, which in turn further decreases insulin sensitivity and increases circulating insulin levels to maintain glucose homeostasis." (PMID 35740366, 2022). "A cross-sectional study found that in AD patients without an APOE4 allele, hyperinsulinemia was also associated with an increased risk of AD and higher insulin was associated with amyloid deposition even before symptom onset as shown by amyloid imaging on positron emission tomography scans." (PMID 35264925, 2022). "IR mainly refers to the decreased sensitivity of muscle, liver and adipose tissue to insulin stimulation, that is, impaired biological response, and long-term IR will lead to the dysfunction of glucose metabolism, which in turn leads to compensatory increase of insulin and hyperinsulinemia." (PMID 35647046, 2022). "Therefore, our study is in line with these reports, suggesting that targeting hyperinsulinemia or insulin signalling on hepatic lipogenesis might be of therapeutic value to treat hepatosteatosis." (PMID 35803934, 2022). "As a consequence, an inflammatory response is elicited that might be worsened by hyperinsulinemia because insulin also enhances the LPS-stimulated expression and secretion of IL-1β and IL-8 from U937 macrophages or primary macrophages differentiated from human-blood mononuclear cells." (PMID 35955975, 2022).
Hyperinsulinemia (continued). "In this latter case, hyperinsulinemia may be the direct consequence of consumption of the “modern” Western diet, overnutrition, decreased hepatic insulin clearance, genetic factors, fetal/metabolic programming, defects in pancreatic β-cells, and loss of pulsatile insulin secretion." (PMID 35897752, 2022). "However, the analysis of individual data revealed that approximately 75% of excess weight participants with hyperinsulinemia at baseline normalized their values after the intervention, while in the physically inactive group, 80% of participants remained with high insulin levels." (PMID 36554976, 2022). "This suggested that fucoxanthin could improve insulin sensitivity and glucose homeostasis through the regulation of the glucose transporter and the decrease in hyperinsulinemia and gluconeogenesis, and impairment of the enzymatic activity of hepatic glucose regulatory enzymes." (PMID 35807489, 2022). "However, in patients with hyperinsulinemia not only is more insulin secreted, but the production of IGFBP-1 and IGFBP-2 is diminished, therefore permitting a higher concentration of active IGF-1 which can stimulate insulin receptors (IR) on endometrial tumor cells." (PMID 35439978, 2022). "Notably, different insulin treatments on HepG2 demonstrated those genetic alterations, suggesting that they might be induced by intrauterine hyperinsulinemia." (PMID 35432202, 2022). "A key role in the pathogenetic mechanisms is played by IR through reductions in whole-body, hepatic, and adipose tissue insulin sensitivity; IR may enhance hepatic fat accumulation by increasing free fatty acid delivery and by the effect of hyperinsulinemia to stimulate anabolic processes." (PMID 35806934, 2022). "However, hyperinsulinemia, with or without T2D, negatively affects the availability and action of insulin at the central level by causing the compensatory downregulation of insulin carriers at the BBB." (PMID 36499613, 2022). "However, single using insulin signal pathway inhibitors can be interfered by hyperinsulinemia." (PMID 35252207, 2022). "However, it is still debated whether insulin resistance and hyperinsulinemia are components of MetS that promote fatty liver or whether NAFLD itself induces chronic hyperinsulinemia due to reduced insulin breakdown." (PMID 35334784, 2022). "In an insulin-resistant status, peripheral tissues have less sensitivity to the action of insulin; therefore, higher concentrations of the hormone than normal are required to maintain normoglycemia, resulting in the development of compensatory hyperinsulinemia." (PMID 34071499, 2021). "Also, the use of insulin contributes to hyperinsulinemia and attributes to carcinogenesis." (PMID 33661912, 2021). "Adipocytes may signal directly to beta cells to control insulin secretion and, therefore, could cause hyperinsulinemia regardless of blood glucose levels." (PMID 34451554, 2021). "Functional deletion of PTPRN (IA-2) in mice results in impaired secretion of insulin, whereas overexpression leads to an increase in DCSVs and insulin secretion, which may have contributed to the hyperinsulinemia that we and others have observed in the KK/HlJ strain." (PMID 33711921, 2021). "Similarly, mRNA levels of the gluconeogenic gene Pepck were increased in both OLE and NMN, but not in NMN + OLE, also likely due to the hyperinsulinemia caused by decreased insulin clearance." (PMID 34948019, 2021). "Moreover, it has been found that hyperinsulinemia drives adipose tissue inflammation in obese mice, suggesting that insulin may also impair systemic insulin sensitivity by specifically enhancing adipose inflammation." (PMID 34360563, 2021). "From the perspective that carbohydrate is not an essential nutrient and the change in foods in recent years has increased the consumption of refined sugar and flour, maybe hyperinsulinemia is the cause of IR and T2DM, as cells protect themselves from excessive glucose and insulin levels." (PMID 34447776, 2021).
Hyperinsulinemia (continued). "Given the independent association of high Fetuin-B levels with low insulin-mediated suppression of adipose tissue lipolysis it is tempting to speculate, that Fetuin-B might represent a crucial element diminishing antilipolytic effects of insulin, e.g., during postprandial hyperinsulinemia." (PMID 34611132, 2021). "One possible mechanism could be the increased insulin concentration observed in the present study compared to others, as hyperinsulinemia accelerates glucose transport and hexokinase activity, which in turn increases intracellular glucose 6-phosphate concentration promoting glycogen synthesis." (PMID 34235576, 2021). "This hypothesis was confirmed in multiple experimental paradigms, including preclinical murine models with hyperinsulinemia (db/db mice and high fat-fed mice) as well as in in vitro experiments using insulin administration to INS1E cells, as well as to rodent and human pancreatic islets." (PMID 33477364, 2021). "Thus, hyperinsulinemia and liver and pancreatic lipotoxicity promote an insulin deficit." (PMID 33928108, 2021). "However, since PIK3CA is ubiquitously expressed in diverse types of tissues, including insulin-responsive tissues, the use of this inhibitor could elicit hyperinsulinemia and diabetes." (PMID 35578699, 2021). "Thus, increased insulin secretion and/or decreased insulin clearance could contribute to hyperinsulinemia during aging." (PMID 34054736, 2021). "A plausible explanation for this could be the pathophysiological link between hyperinsulinemia and hypertension, which is believed to be related to the prolonged actions of insulin on the sympathetic nervous system, although the mechanistic process has not been fully elucidated." (PMID 33924538, 2021). "Both GDM and HDP are characterized by hyperinsulinemia; the cells become resistant to insulin action, so the pancreas secretes more in an attempt to achieve a normal response, which contributes to development of adiposity resulting from the anabolic action of insulin." (PMID 34769624, 2021). "Regardless of the cause of hyperinsulinemia, it is unclear whether this transiently high insulin level plays a role in DEP." (PMID 34566890, 2021). "In addition, chronic hyperinsulinemia reduces insulin sensitivity and metabolic functions of brown adipocytes, and this leads in mice to increased body weight gain, fat mass and impaired glucose intolerance with reduced energy expenditure and insulin sensitivity." (PMID 34360563, 2021). "The hyperinsulinemia/insulin signaling pathway may play a role in the development of breast cancer." (PMID 34485124, 2021). "Besides, the antagonism of clozapine at α2 receptors expressed on β-cells could reduce the inhibitory effect of the sympathetic system on insulin secretion, and thus have a role in hyperinsulinemia." (PMID 33800403, 2021). "Likewise, high levels of insulin, coming from the splanchnic circulation, are not properly metabolized inside the liver and directly cause systemic hyperinsulinemia." (PMID 33800465, 2021). "Despite plasma hyperinsulinemia, AD brain demonstrates reduced endothelial insulin receptors and decreased insulin in cerebrospinal fluid (CSF) suggesting reduced transport of insulin into brain, where insulin has myriad effects on all brain cell types including anti-amyloid activity." (PMID 34769257, 2021). "Although insulin therapy achieves effective glycemic control, it may aggravate hyperinsulinemia." (PMID 34579668, 2021). "Compensatory hyperinsulinemia increases the bio-availability of androgen and its production in the ovary and adrenal gland by reducing the concentration of sex hormone-binding globulin, and high levels of androgen and insulin in the plasma can affect the periodic exfoliation of the endometrium." (PMID 34975540, 2021).
Hyperinsulinemia (continued). "Similarly, our results on elevated insulin levels in female diabetic rats may suggest that the decreased IRS-2 expression observed in the aorta could be in part due to hyperinsulinemia in this group." (PMID 34366875, 2021). "In the same manner than in lean mice exposed to IH, we showed that high fat diet upregulated cardiac insulin/Akt signaling in the basal state that could result from hyperinsulinemia, whereas response to insulin stimulation was blunted, suggesting an insulin resistance state." (PMID 33682327, 2021). "Since the overfed mares in the present study were previously shown to exhibit hyperinsulinemia in response to an oral glucose challenge, it seems reasonable to propose that elevated plasma and FF insulin concentrations may have compromised oocyte and embryo developmental competence." (PMID 33535548, 2021). "The fetal insulin hypothesis would predict that affected individuals have a low birthweight, yet individuals with HNF1A-MODY have normal birthweights and inheritance of HNF4A-MODY is associated with fetal and neonatal hyperinsulinism and macrosomia." (PMID 33569631, 2021). "Additionally, to our knowledge, vinculin has not been reported as an underlying mechanism of hyperinsulinemia but is known to be a substrate of protein kinase C, which is part of the insulin signaling pathway." (PMID 32596266, 2020). "Therefore, insulin-induced autophagy suppression and premature senescence may be responsible for the poor osteogenic differentiation of H-BMSCs under hyperglycemic and hyperinsulinemia conditions." (PMID 32017705, 2020). "The link between insulin clearance and atherosclerosis is further underlined by findings from rodents: knockout of CEACAM1, the central protein for insulin clearance in the liver, causes hyperinsulinemia and marked endothelial dysfunction and formation of atherosclerotic plaques." (PMID 33384433, 2020). "Notably, although the fasting blood glucose levels remained similar in Stk25–/– and WT mice in this study, Stk25-KO mice exhibited suppressed hyperinsulinemia and an increase in whole-body glucose tolerance and insulin sensitivity at the end of the high-fat feeding period." (PMID 33170807, 2020). "As insulin plays a central role in cell proliferation, fetal hyperinsulinemia, resulting in downregulation of insulin signalling components (as has been shown in adult peripheral tissues), may be an underlying cause of resistance to the proliferative effects of insulin in fetal tissues." (PMID 32919096, 2020). "Among non-diabetic patients, hyperinsulinemia associated with reduced insulin sensitivity may play a role in the pathogenesis of prostate carcinoma." (PMID 32132977, 2020). "Since insulin promotes hepatic lipogenesis, reducing hyperinsulinemia may help in treating HS." (PMID 32286259, 2020). "Under prediabetic, insulin-resistant conditions, pancreatic islets respond to increased metabolic overload with increased β cell mass and elevated insulin secretion, which generates compensatory hyperinsulinemia to maintain blood glucose levels within the normal range." (PMID 32092075, 2020). "However, as increased birth weight indicates prenatal hyperinsulinism and increased levels of insulin promote fetal anabolism, it may simply reflect disease severity and thus associate with adverse neurodevelopmental outcome." (PMID 33424766, 2020). "Animal studies to date have shown that hyperinsulinemia in β-cells occurs when insulin signaling downstream of the insulin receptor is impaired in insulin target organs and bacterial endotoxins can stimulate the production of cytokines and consequently IR in insulin target organs." (PMID 30039349, 2019). "Therefore, the dysregulation of inositol metabolism may lead to decreased insulin sensitivity, hyperinsulinemia, inhibition of the maturation of follicles, and the development of PCOS." (PMID 31885557, 2019).
Hyperinsulinemia (continued). "Similarly CRMP slows E0771 tumor growth, similar to its effect to slow colon tumor growth, by reversing hyperinsulinemia and insulin-dependent increases in tumor glucose uptake and oxidation, without any direct effect to alter tumor cell metabolism or division." (PMID 31867105, 2019). "Moreover, the hyperinsulinemia promotes the resistance of insulin in reverse." (PMID 30621321, 2019). "However, restoring hyperinsulinemia by chronic subcutaneous insulin infusion increased tumor glucose uptake and oxidation to levels measured in untreated HFD tumor-bearing mice, confirming that tumor glucose uptake and oxidation are dynamic and insulin-responsive." (PMID 31867105, 2019). "Then, it would be plausible to assume that a possible hyperinsulinemia in MSG-treated animals could accentuate insulin lipogenic effects, inducing higher lipids synthesis and deposition into the adipocytes, contributing to the increased total fat and adiposity index observed in our study." (PMID 30738429, 2019). "However, in the present study, removal of the AgRP peptide did not reverse the hyperinsulinemia or the effects on insulin signaling genes caused by chronic corticosterone." (PMID 30794724, 2019). "The activity of insulin (in the skeletal muscle, liver, adipose tissue and kidneys) is compromised by the insulin resistance pathways that aggravate its secretion and resistance, either by deposition of fatty acids in skeletal muscles or by peripheral hyperinsulinemia." (PMID 31756981, 2019). "After observing the ability of dapagliflozin to slow E0771 breast tumor growth by reversing hyperinsulinemia, we asked whether similar effects would be seen as a result of reducing circulating insulin concentrations with an agent that works through a divergent mechanism." (PMID 31867105, 2019). "Thus, the present results suggest that more research is needed to better understand the relationship between hyperinsulinemia and IR, with the possibility that different modes of treatment may be necessary to suit different forms of insulin dysregulation." (PMID 30808423, 2019). "Thus, correction of hyperinsulinemia is an important target of insulin sensitizer agents." (PMID 29768504, 2018). "Compared with single nutrients or food items, a dietary pattern may more comprehensively affect insulin; we therefore previously developed an index to assess the insulinemic potential of whole diets, termed the empirical dietary index for hyperinsulinemia (EDIH)." (PMID 30740588, 2018). "Thus, hyperinsulinemia under insulin-resistant conditions in humans and animals may be one reason for the increased INHBE gene expression in the liver under pre-diabetic conditions." (PMID 29596463, 2018). "The exercise intervention improved maternal insulin sensitivity; therefore, maternal hyperinsulinemia could play a role in mediating offspring cardiac dysfunction but clearly improving insulin sensitivity was insufficient to prevent the increased blood pressure in the offspring." (PMID 30293577, 2018). "Therefore, the mechanisms of increased INHBE expression by insulin under insulin-resistant conditions may be similar to the mechanisms of enhanced lipogenic gene expression in hyperinsulinemia under insulin-resistant conditions." (PMID 29596463, 2018). "Hence, the preprandial hyperinsulinemia could lead to activation of insulin signaling, abrogating FOXO1 activity." (PMID 30532187, 2018). "It is well-established that hyperinsulinemia is a major risk factor for equine laminitis and that elevated circulating insulin concentrations can trigger the condition, regardless of whether the animal is insulin-resistant or not." (PMID 29958298, 2018). "Similarly, the presence of hyperinsulinemia observed in diabetic patients and frequent percutaneous procedures during insulin therapy and glycemic assessment may play a role." (PMID 30423991, 2018). "Therefore, HFDs lead to an increase in insulin release from β cells and thus hyperinsulinemia." (PMID 30483273, 2018).